OR1R1 (olfactory receptor family 1 subfamily R member 1)
Description:
Odorant receptor.
Synonyms: OR1R1P; OR17-1; OR17-01; OR1R2P; OR1R3P; OR20A1P
Gene: Protein-coding gene on chromosome 17 (3,385,930 to 3,386,874, forward strand). Ensembl gene ENSG00000180042.
Subcellular location: Membrane
Gene Ontology:
Molecular function: odorant binding; olfactory receptor activity
Biological process: detection of chemical stimulus involved in sensory perception of smell; G protein-coupled receptor signaling pathway
Cellular component: membrane
Homologues: Orthologues: chimpanzee OR1R1P (83% identical), mouse Or1r1 (82% identical), guinea pig OR1R1P (79% identical), rat Or1r1 (78% identical). Paralogues in human: OR1K1 (43% identical), OR1L6 (42% identical), OR1F1 (41% identical), OR1L4 (41% identical), OR1E1 (41% identical), OR1G1 (41% identical), OR1N2 (41% identical), OR1E2 (40% identical), OR7D4 (40% identical), OR1B1 (40% identical), OR1J4 (40% identical), OR1M1 (39% identical), and 116 more.